IL20 (interleukin 20)
Diseases named in the same sentence as IL20 in open-access papers (continued):
Sharing a sentence is not in itself a finding about the gene and the disease.
psoriasis (continued). "The biphasic response suggests that the aberrant IL-20 expression in psoriasis impedes DC migration, which could be a part of the processes that precipitates the dysregulated inflammatory response associated with this disease." (PMID 26819710, 2016). "The higher the IL-20 concentration was, the more severe the psoriasis was on average." (PMID 26146462, 2015). "In psoriasis IL-17A, IL-17F, IL-22 and IL-20 act on keratinocytes leading to epidermal hyperplasia." (PMID 25153527, 2014). "IL-19, like IL-20, has been shown to be produced under inflammatory conditions and is thought to play an important role in the pathogenesis of some inflammatory diseases, such as psoriasis." (PMID 23303806, 2013). "The effects of alefacept treatment on IL-20 expression in the synovium of patients with psoriasis and PsA are currently unknown." (PMID 23006144, 2012). "Interleukin-20 (IL-20) is a key proinflammatory cytokine involved in the pathogenesis of psoriasis." (PMID 23006144, 2012). "It has been reported that the cytokines IL-19, IL-20 and IL-24 are highly expressed in the inflammatory sites of psoriasis, and may thus mediate the progression of psoriasis." (PMID 22792286, 2012). "Like IL20, IL19 is also associated with psoriasis, another inflammatory disease." (PMID 16959027, 2006). "Apart from significant genetic association of Hepatitis C virus clearance with IL10/19 and IL20, and psoriasis with IL19/20 and IL24, to our knowledge no additional disease association studies with these cytokine genes have been conducted." (PMID 16959027, 2006). "Therefore, IL-20 seems to be involved in the pathogenesis of psoriasis." (PMID 29690863, 2018). "Our findings show that psoriasis DEGs can be explained in part by shifts in the cellular composition of psoriasis lesions (e.g., KCs and inflammatory cells), and in part by the response of KCs to cytokines, particularly those from the IL-1, IL-17 and IL-20 families." (PMID 23915137, 2013). "We identified five cytokines and receptors that intersected between urticaria, atopic dermatitis, and psoriasis: IL36G, IL20, IL1B, CXCR1, and CXCL1." (PMID 40159643, 2025). "CCL20, IL-6, IL-20, IL-17C, and PI3 were previously found to be elevated in patients with psoriasis." (PMID 39224116, 2024). "In this study, TAN significantly inhibited the levels of iNOS, TNFα, IL-6, IL-10, IL-20, MIF, and MCP-1 in psoriasis mice, which had a wide range of inflammatory inhibitory effects." (PMID 38832986, 2024). "In general, proinflammatory cytokines and factors stimulating proliferation in psoriasis are produced mainly by T cells (IL-17, IL-21, IL-22, IFN-γ), DCs (TNF-α, IL-6, IL-20, IL-23, NO), and KCs (antimicrobial peptides (AMPs), IL-20, chemokines)." (PMID 38642273, 2024). "A number of serum analytes identified by Olink analysis, including PI3, IL-17C, CCL20, IL-20, IL-6, CXCL9, and CXCL10, have been previously identified as being elevated in serum samples of patients with psoriasis." (PMID 39224116, 2024). "Estimated odds of having psoriasis increased by about 3% if COMP increased by about 1 ng/mL, by about 25.8% if IL-20 increased by about 1 pg/mL, and almost twice if OPG increased by about 1 pmol/L." (PMID 26146462, 2015). "Targeting the interactions between IL-22R1 and cytokines such as IL-20, IL-24, IL-17, TNF, and IL-1β could improve clinical outcomes in psoriasis treatment." (PMID 40303401, 2025). "An anti–IL-20 antibody evaluated in a phase 1 trial of in patients with psoriasis did not further progress into clinical development (NCT01261767)." (PMID 39224116, 2024). "Results of the conducted study suggest that COMP, OPG, IL-20, and OPG/sRANKL ratio may appear useful biomarkers of bone and cartilage involvement in psoriasis." (PMID 26146462, 2015). "Data from mice suggests that this elevation can augment epidermal hyperplasia, since overexpression of either IL-20 or IL-24 (but not IL-19) elicits a psoriasis-like phenotype." (PMID 23915137, 2013).
psoriasis (continued). "Also IFN-γ-induced, but not IL-22-induced IL-6 and IL-20, two psoriasis-related cytokines were inhibited by this drug." (PMID 30581877, 2018). "Although PI3, BD-2, and IL-20 showed the highest correlation with PASI in our dataset, these mediators do not seem to play a central role in psoriasis." (PMID 39224116, 2024). "Most well known psoriasis related genes activated in non-lesional skin are IL6, IL22, IL36A, IL36G, IL19, IL20, S100A7 and S100A12." (PMID 25897967, 2015).
rheumatoid arthritis (38 papers, 2012 to 2025). A chronic, systemic autoimmune disorder characterized by inflammation in the synovial membranes and articular surfaces. "Excessive IL-20 expression is associated with chronic inflammatory diseases, such as rheumatoid arthritis and osteoporosis." (PMID 35681232, 2022). "Many studies have demonstrated that IL-20 is associated with several inflammatory diseases, such as rheumatoid arthritis, atherosclerosis, cancer, and liver fibrosis via regulating cytokines and chemokines." (PMID 32028746, 2020). "IL-20 is a pleiotropic cytokine that is associated with inflammatory diseases, such as rheumatoid arthritis and atherosclerosis." (PMID 28514748, 2017). "IL-20, a cytokine with powerful inflammatory, angiogenic, chemoattractive, and osteoclastogenic properties, plays a critical role in various stages of rheumatoid arthritis (RA) progression, as well as in obesity-related inflammation and insulin resistance." (PMID 41551693, 2025). "Beyond its link to rheumatoid arthritis by activating synovial fibroblasts, IL-20 also contributes to the development of nephritis by prompting kidney mesangial cells to produce various pro-inflammatory molecules, including MCP-1, RANTES, IP-10, and IL-6." (PMID 39813538, 2025). "Recently, clinical trials and animal experiments have found elevated serum IL-20 levels in rheumatoid arthritis, osteoporosis, and cancer-related osteolytic diseases." (PMID 36835229, 2023). "For example, circulating IL-20 protein levels (elevated by HU in our current study) are also increased at the early stages of rheumatoid arthritis and decreased after 6 months of treatment." (PMID 34230490, 2021). "We recently found that IL-20 is upregulated in rheumatoid arthritis synovial fibroblasts (RASFs) and several cancer cells including breast cancer, oral cancer, and prostate cancer." (PMID 29690863, 2018). "IL-20 is a proinflammatory cytokine that causes inflammation, angiogenesis, chemotaxis, and apoptosis, and is involved in the pathogenesis of psoriasis, atherosclerosis, stroke, rheumatoid arthritis (RA), acute and chronic renal failure, and prostate cancer." (PMID 28426699, 2017). "Interleukin (IL)-20 is a proinflammatory cytokine involved in rheumatoid arthritis, atherosclerosis, and osteoporosis." (PMID 29242565, 2017). "Interleukin (IL)-20 is a proinflammatory cytokine involved in the pathogenesis of rheumatoid arthritis." (PMID 28426699, 2017). "IL-20 is a pleiotropic cytokine involved in cancer, atherosclerosis, rheumatoid arthritis, and stroke." (PMID 28514748, 2017). "As a comparison, the mean concentration of IL-20 in serum from patients suffering rheumatoid arthritis was reported to be 0.282 ng/ml." (PMID 26819710, 2016). "IL-20 family cytokines facilitate communication between epithelial and leukocytes and IL-20 is involved in psoriasis, stroke and rheumatoid arthritis." (PMID 27806114, 2016). "IL-20 is known to affect migration of neutrophils, chemotaxis of synovial fibroblasts chemotaxis in rheumatoid arthritis, and vascular tube-formation by endothelial cells." (PMID 26819710, 2016). "NNC0109-0012 is the first monoclonal antibody targeting IL-20 (anti‒IL-20) and is being considered for the treatment of PsO, rheumatoid arthritis, and other inflammatory diseases." (PMID 26252485, 2015). "Moreover, IL-20 has been implicated to play an important role in several autoimmune diseases that include rheumatoid arthritis (RA), lupus nephritis, and Crohn disease." (PMID 23006144, 2012). "IL-20 is emerging as a potent angiogenic, chemotactic, and proinflammatory cytokine related to several chronic inflammatory bone disorders likes intervertebral disc herniation, rheumatoid arthritis (RA), osteoporosis, and bone fracture." (PMID 30250404, 2018). "IL-20 is involved in inflammation, angiogenesis, arteriogenesis, and chemotaxis, all of which are important for the pathogenesis of psoriasis, atherosclerosis, rheumatoid arthritis, and ischemic disorders." (PMID 29242565, 2017).
rheumatoid arthritis (continued). "IL-20 promoted osteoclast differentiation and blockading IL-20 might provide a novel therapeutic approach for rheumatoid arthritis and osteoporosis, which support the notion that IL-20 is important for regulating bone homeostasis." (PMID 27075747, 2016). "Differences between the serum levels of cytokines and local expression are not uncommon and have been described for example for IL-20 in patients with rheumatoid arthritis." (PMID 38799447, 2024). "The anti-IL-20 antibody was well tolerated and showed no safety issues in healthy volunteers and patients with rheumatoid arthritis, which demonstrated the safety of anti-IL-20 as a new therapeutic drug for DED." (PMID 35681232, 2022).
atherosclerosis (17 papers, 2012 to 2023). A disease characterized by the build-up of fatty material and calcium deposition in the arterial wall resulting in partial or complete occlusion of the arterial lumen. "The aim of the study was to evaluate the association of two IL-20 polymorphisms (rs1400986 and rs1518108) with subclinical atherosclerosis (SA), cardiovascular risk factors and IL-20 levels in a cohort of Mexican individuals." (PMID 31947776, 2020). "The macro vascular complication atherosclerosis is common in T2D subjects and indeed associated with IL-20 activity." (PMID 26162095, 2015). "It was found that IL20 cytokine has been involved in the developing of atherosclerosis, however, at the present, there are not studies that analyzed the association of the polymorphisms located in the gene that encodes this cytokine with the presence of atherosclerosis." (PMID 31947776, 2020). "In apolipoprotein E deficient (apoE−/−) mice, IL-20 is able to enhance IL-6 and TNF-α expression and accelerate the development of atherosclerosis." (PMID 29690863, 2018). "Other studies have also suggested a potential role of IL-20 in atherosclerosis and angiogenesis." (PMID 23094074, 2012).
breast carcinoma (13 papers, 2015 to 2022). "IL-20 expression in breast cancer tissue was associated with a higher mitotic rate, advanced tumor stage, and bone metastasis." (PMID 31847214, 2019). "Studies have also associated IL-20 with breast cancer metastasis to bone." (PMID 33809315, 2021). "IL-20 has recently been reported to play a pivotal role in tumor progression, and its expression has been strongly associated with the clinical outcomes of breast cancer patients." (PMID 28514748, 2017). "IL–20 is associated with tumor promotion in the pathogenesis of oral, bladder, and breast cancer." (PMID 26440411, 2015). "Anti-IL–20 monoclonal antibody (mAb) 7E decreased osteolytic bone lesions in mouse models of breast cancer and protected ovariectomized mice against osteoporotic bone loss, both of which support the notion that IL–20 is critical for regulating of tumor-mediated osteolysis." (PMID 26440411, 2015). "Inhibition of IL-20 with a monoclonal antibody reduced mammary fad pad growth of 4T1 breast cancer cells and reduced breast cancer cell colonization in bone and osteolysis in vivo." (PMID 33809315, 2021). "IL-20 and IL-26 were discovered to promote proliferation and migration of bladder cancer, breast cancer, and gastric cancer cells, while IL-24 was found to inhibit the proliferation and metastasis of melanoma, prostate cancer, and OC." (PMID 34114949, 2021). "Previously, IL-20 was reported to promote the progression of prostate cancer, oral cancer, and breast cancer 20-22." (PMID 33456560, 2021). "Our previous studies have demonstrated that IL-20 promotes tumor growth and increases metastasis in hepatocellular carcinoma, breast cancer, prostate cancer, and oral cancer." (PMID 32929072, 2020). "IL-20 determines an increase in breast cancer cell growth, migration, and protease expression in vitro." (PMID 31847214, 2019). "In 4 T1 breast cancer-induced osteolytic bone metastasis model, anti-IL-20 mAb 7E treatment not only inhibited bone colonization but also prevented the osteolytic bone loss in mice." (PMID 29690863, 2018). "The data suggest that IL-20 is a key factor involved in the progression of breast cancer and anti-IL-20 mAb has a therapeutic potential to protect breast-cancer induced osteolysis." (PMID 29690863, 2018). "We previously found that both IL-20 and its receptors (IL-20R1 and IL-20R2) are overexpressed in the sites of primary tumor and bone-metastasis in breast cancer patients, and the higher expression of IL-20 is correlated with poorer clinical outcome." (PMID 29690863, 2018). "In breast cancer-induced osteolytic bone metastasis model, anti-IL-20 mAb 7E treatment not only inhibited the bone colonization but also protested against the osteolytic bone loss in mice." (PMID 29690863, 2018). "In summary, our findings have shown that IL-20 expression in breast cancer is regulated by a transcriptional complex composed of transcription factors, including ER(α), GATA3, and FOXA1, as well as a transcriptional elongation factor, Ell3." (PMID 28514748, 2017). "In this study, we show that Ell3, ER(α), GATA3 and FOXA1 form a transcriptional complex to regulate IL-20 expression in ER(+) breast cancer cell lines." (PMID 28514748, 2017). "Consistent with the results for MCF7 cells, IL-20 expression in another ER(+) breast cancer cell line, T47D, was also enhanced by estrogen treatment and suppressed by the depletion of ER(α)." (PMID 28514748, 2017). "Recent evidence indicates that IL-20 is a therapeutic target in various cancers, including breast cancer, and that an anti-IL-20 monoclonal antibody has therapeutic potential for alleviating inflammation and osteolysis associated with tumor progression." (PMID 28514748, 2017).
breast carcinoma (continued). "In this study, we demonstrated that ER(α), GATA3 and FOXA1 form a transcriptional complex with Ell3 to regulate IL-20 expression in ER(+) breast cancer cells." (PMID 28514748, 2017). "IL-20 expression is regulated by a transcription elongation factor, Ell3, in estrogen receptor-positive (ER(+)) breast cancer cells." (PMID 28514748, 2017). "We have revealed an important role for KMT2B in the epigenetic transcriptional regulation of cytokine IL-20, and other ERα-responsive genes, in breast cancer cells." (PMID 27806114, 2016). "Analysis by immunohistochemistry (IHC) showed that IL-20 was abundantly expressed in 80.9% of ER-positive breast cancer samples (P < 0.001)." (PMID 27806114, 2016). "Our IHC analyses showed that the majority of IL-20 positive breast cancer tissues we examined are also ER-positive." (PMID 27806114, 2016). "IL-20 dose dependently increased breast cancer cell migration in vitro." (PMID 33809315, 2021). "IL-20 and KMT2B expression were also associated with ERα-positive breast cancer tissues." (PMID 27806114, 2016). "IL–20 is involved in several inflammatory diseases, such as rheumatoid arthritis, atherosclerosis, psoriasis, osteoporosis, oral cancer, and breast cancer." (PMID 26440411, 2015). "We also found that the expression level of IL20RA ligands IL-19, IL-20, and IL-24 was dramatically elevated in the serum of breast cancer patients compared to that of healthy donors, indicating that IL20RA signaling may play an important role in the progression of cancer." (PMID 33456560, 2021). "We developed the anti-IL-20 monoclonal antibody (mAb) 7E, which was shown to neutralize the in vitro and in vivo activity of human and mouse IL-20, and showed that 7E treatment effectively alleviated inflammation and suppressed tumor growth in breast cancer and prostate cancer mouse models." (PMID 32929072, 2020). "IL20 was found to be an ERG, and its expression at the mRNA and protein levels in breast cancer cells was up-regulated by estrogen treatment." (PMID 35976950, 2022). "IL-20 upregulates CTSK and MMP-9 to promote the proliferation and migration of breast cancer cells in vitro." (PMID 36005209, 2022). "Amplification of IL19, IL20, and IL24 co-occurs in ~9% of breast cancer patients, while the rate of IL26 amplification is only 2.4%." (PMID 33456560, 2021). "Therefore, IL-20 might provide a suitable microenvironment for breast cancer metastasis." (PMID 29690863, 2018). "The same assay was also performed using two additional ERα-positive breast cancer cell lines, ZR751 and T47D, resulting in a similar downregulation of ERα, IL20 and pS2 by GLI1 knockdown." (PMID 27689403, 2016). "The most frequent gains found in our BRCAX tumors have been previously observed to be amplified in breast cancer, and contain at least four genes of interest PDE4DIP/Myomegalin, IL19, IL20 and FAIM3." (PMID 26979459, 2016). "Because Ell3 is an additional factor to the triple complex of ER(α), GATA3 and FOXA1 and this complex fine-tunes the expression level of IL-20, it will be essential to assess the clinical meaning of the expression of FOXA1 in combination with the expression of Ell3 in ER(α) breast cancer patients." (PMID 28514748, 2017). "In a previous study, we reported that transcription elongation factor Ell3 directly regulates IL-20 expression in an ER(+) breast cancer cell line, MCF7, but not in ER(−) breast cancer cell lines." (PMID 28514748, 2017). "In this study, we showed that expression of the pro-inflammatory cytokine IL-20 was regulated by a transcriptional complex composed of the transcription factors ER(α), GATA3, and FOXA1 and the transcriptional elongation factor Ell3 in ER(+) breast cancer cells." (PMID 28514748, 2017). "Inhibition of IL-20 and KMT2B may have therapeutic benefits in ERα-positive breast cancer." (PMID 27806114, 2016). "We examined IL-20 mRNA levels across a panel of breast cancer subtypes and normal breast tissues." (PMID 27806114, 2016).